IGF2 (insulin like growth factor 2)
Diseases named in the same sentence as IGF2 in open-access papers (continued):
Sharing a sentence is not in itself a finding about the gene and the disease.
pancreatic cancer (continued). "CpG island methylator phenotype (CIMP)-high status [three/four or more methylated promoters among CACNA1G, CDKN2A, IGF2, and RUNX3] was observed in 12% (34/283) of the pancreatic cancer cases." (PMID 25797243, 2015). "QRT-PCR was performed to evaluate the levels Shh, Gli1, IGFBP6, IGF2, PCNA, Bcl-2, Bax and Bak1 mRNA in pancreatic cancer tissues (n = 6) and corresponding cancer side tissues (n = 6)." (PMID 19736394, 2009). "On the other hand, the expression of IGF2 was very low in pancreatic cancer and was not affected by cyclopamine or RNAi for Gli1, which means the regulation of IGF2 expression is independent of Shh-Gli1 signaling pathway in pancreatic cancer." (PMID 19736394, 2009). "Excess IGFBP5 has been shown to regulate myotube differentiation probably via modulation of IGF-2 signaling, however, whether IGFBP-3, which predominantly binds to IGF-1 and exhibits the greatest induction in pancreatic tumors, affects myogenesis is largely unknown." (PMID 26975989, 2016).
Anxiety (27 papers, 2012 to 2026). Intense feelings of nervousness, tension, or panic often arise in response to interpersonal stresses. "Insulin‐like growth factor 2 (IGF2) is expressed in the choroid plexus (CP) within the subventricular zone (SVZ) neurogenic niche, and global loss of IGF2 leads to increased anxiety." (PMID 40457890, 2025). "Moderating effects of sex on the association between maternal anxiety and methylation were found for IGF2/H19 and LINE1 CpGs." (PMID 34572069, 2021). "Among those, we observed genes that have been associated with PTSD in previous human studies (e.g., DRD2 and HTR2a) or linked to anxiety or PTSD-like behaviors in humans or animal models (Igf2, Grm2, Clock, Trhr)." (PMID 30705647, 2018). "We report strong and consistent evidence of an association between maternal anxiety and decreased IGF2/H19 ICR methylation at the major CpG sites across the region investigated and these associations persisted when accounting for a range of covariates." (PMID 27023171, 2016). "Two other studies using cord blood have investigated the association between anxiety, IGF2 and ICR methylation, but they assayed slightly different gene regions compared with our own study." (PMID 27023171, 2016). "This study provides consistent evidence in a large, well-characterized population-based birth cohort of a prospective association between maternal anxiety during pregnancy and reduced infant IGF2/H19 ICR cord blood methylation." (PMID 27023171, 2016). "IGF2, a pleiotropic polypeptide abundantly expressed in CNS, influences neurogenesis and neuroinflammation, with dysregulated expression linked to CNS disorders such as anxiety and Alzheimer's disease 44-46." (PMID 41424856, 2026). "Hence, we performed elevated plus maze (EPM) and light/dark transition tests to assess the effect of IGF2 loss exclusively in both Prlr‐containing cells or CP tissue on post‐partum anxiety levels." (PMID 40457890, 2025). "However, in another study, maternal anxiety was associated with decreased IGF2/H19 ICR DNA methylation in cord blood of female neonates." (PMID 34572069, 2021). "Finally, we assessed the moderating influence of candidate genes whose level of methylation is associated with the Nr3c1 genotype on anxiety-like behavior: Ank3, Avp, Avpr1a, Avpr1b, Bdnf, Cacna1c, Cyp11b1, Cyp11b2, Fkbp5, Hsd11b1, Igf2, Morc1, Nr3c1, Oxt, Oxtr, Pclo, Slc6a4." (PMID 30655507, 2019). "For example, using a mouse model of Igf2 dysfunction, where only placental expression was reduced, we demonstrated that a foetus:placenta imbalance can lead to adult-related changes in anxiety-related behaviours." (PMID 39141687, 2024). "Placenta-specific depletion of the insulin-like growth factor 2 gene (Igf2) in transgenic mice resulted in increased offspring anxiety." (PMID 36766778, 2023). "Although Bdnf and Igf2 are well known regulators of anxiety behavior and fear extinction, the propagation of information from sperm miRNAs to the brain of adult mice is unclear." (PMID 35466187, 2022). "Igf2-inducible knockout mice displayed increased anxiety; IGF2 was shown to be one of the anxiety-related differentially methylated genes in humans." (PMID 36614124, 2022). "Male F1 progeny displayed altered anxiety-related behaviors and significantly increased Igf2 mRNA expression in the hippocampus." (PMID 35466187, 2022). "For boys, there was a negative association between maternal anxiety during the third trimester and the methylation level of IGF2/H19 CpGs, with higher maternal anxiety predicting lower methylation levels." (PMID 34572069, 2021). "Further, exposure to an enriched environment during adolescence corrected the reduction of hippocampal IGF-2 expression, normalized anxiety-like behavior, and reversed dendritic retraction in the adult offspring." (PMID 35873062, 2021).
Anxiety (continued). "While we observed lower DNA methylation in IGF2/H19-CpG1, 4, and 6 in boys exposed to higher levels of maternal anxiety in the third trimester, we observed higher DNA methylation in these locations for girls." (PMID 34572069, 2021). "A previous study with rats reported that developmental exposure to morphine increased anxiety-like behaviors, but such effects were mitigated by stimulating IGF-2 signaling and providing environmental enrichment." (PMID 34312305, 2021). "Previous studies of IGF2 methylation have also found associations with ADHD symptoms and prenatal maternal anxiety." (PMID 30176105, 2019). "Further work is required to characterize the relationships between maternal anxiety, IGF2/H19 ICR methylation, birth outcomes and subsequent long-term offspring health." (PMID 27023171, 2016). "This study found a negative association between maternal anxiety and methylation levels in boys and a positive association in girls for IGF2/H19 ICR." (PMID 36430406, 2022). "However, for girls, there was a positive association between maternal anxiety during the third trimester and the methylation level of IGF2/H19 CpGs, with higher maternal anxiety predicting higher methylation levels." (PMID 34572069, 2021). "This study suggests that IGF-2 and an enriched environment may be potential forms of intervention to prevent anxiety and brain atrophy in the offspring of parental opioid exposure." (PMID 35873062, 2021). "Thus, we added evidence to the suggestion that maternal anxiety during pregnancy can influence IGF2/H19 in a sex-specific manner." (PMID 34572069, 2021). "Treatment with dicholine succinate reduced the anxiety scores of stressed mice in the dark/light box paradigm, precluded stress-induced decreases of long-term contextual memory in the step-down avoidance test and hippocampal gene expression of IGF2." (PMID 22989159, 2012). "Interestingly, overexpression of IGF-2 prevented anxiety-like behaviors in these offspring." (PMID 35873062, 2021). "Previously, we have shown that pregnancy anxiety is linked to fetal DNA methylation in the glucocorticoid receptor gene (NR3C1), which is a key player in the hypothalamic-pituitary-adrenal axis, and to DNA methylation of imprinted genes IGF2 and GNASXL important in fetal growth and development." (PMID 29026448, 2017). "Using CP‐derived IGF2 knockout mouse models, we have measured Prlr expression in CP tissue, SVZ mitogenesis, olfaction, and anxiety‐like behavior using an elevated plus maze (EPM) and light/dark transition test (LDTT)." (PMID 40457890, 2025). "In agreement with the under-expression of the neuropeptide insulin-like growth factor 2 (IGF2) transcript isoform in the amygdala of MIA relative to control pigs, IGF2 treatment can reverse behavior disorders such as anxiety-like phenotypes." (PMID 33834688, 2021). "Annotation of the anxiety-related DMRs to genes revealed 183 genes, many of which were known stress-related genes such as NAV1, IGF2, GNAS, and CRTC1." (PMID 29225348, 2017). "Previous work has shown that global removal of Igf2 in adulthood leads to a reduction in NSC turnover in the SVZ, increased recruitment of immature neurons to the olfactory bulb accompanied by heightened anxiety‐like behavior and hyposmia in mice." (PMID 40457890, 2025). "There were no sex interactions in the third trimester on other CpGs of IGF2/H19, or on the effect of maternal anxiety in the first and second trimester on any of the CpG of IGF2/H19." (PMID 34572069, 2021). "For IGF2/H19 ICR, we found a negative association between maternal anxiety and methylation levels in boys, in contrast to a positive association in girls." (PMID 34572069, 2021). "This hypothesis was not supported by the present data, which rather suggest that CP‐derived IGF2 does not affect SVZ mitogenesis during lactation or anxiety levels in our mouse models post‐partum, when assessed in both the EPM and light/dark transition test." (PMID 40457890, 2025).
islet cell tumor (27 papers, 1998 to 2025). "Evidence suggests that high-molecular-weight IGF-2, secreted by non-islet cell tumors of mesenchymal origin, interacts with insulin and IGF-1 receptors, as well as binding proteins, to induce the expression of hexokinase and other glycolytic enzymes." (PMID 40568267, 2025). "Non–islet cell tumor hypoglycemia as a result of insulin-like growth factor (IGF)-2 secretion is rare." (PMID 40270996, 2025). "Overproduction of insulin-like growth factor-2 (IGF2) or its precursor is the main mechanism related to non-islet cell tumor hypoglycemia." (PMID 27134683, 2016). "In patients with non-islet cell tumor the pool of big-IGF2 increases and 80 % of this molecule is bounded to IGFBP3 only, forming a lower molecular weight that crosses the endothelial barrier and acts on insulin receptors." (PMID 27134683, 2016). "IGF‐2‐mediated hypoglycaemia is a rare manifestation of non‐islet cell tumours." (PMID 38411039, 2024). "The patient's laboratory results revealed low levels of IGF-1 (15 ng/ml), normal levels of IGF-2 (395 ng/ml), and an elevated IGF-2-to-IGF-1 ratio of 26:1, indicating non-islet cell tumor hypoglycemia." (PMID 39867043, 2024).
osteosarcoma (27 papers, 2009 to 2025). A usually aggressive malignant bone-forming mesenchymal neoplasm, predominantly affecting adolescents and young adults. "Silencing of Wnt inhibitory factor 1(WIF1), p14ARF, and RASSF1A by DNA hypermethylation and loss-of-imprinting in IGF2 and H19 have also been shown to occur in osteosarcoma." (PMID 26802029, 2016). "The expression of insulin-like growth factor 2 (IGF2) has been shown to induce a state of dormancy in osteosarcoma, leading to acquired resistance against chemotherapeutic drugs and the subsequent, future endangerment of minimal residual disease." (PMID 36430404, 2022). "Chronic exposure of osteosarcoma cells to IGF2 or insulin in combination with serum deprivation, successfully established an in vitro dormancy and drug-resistance model in osteosarcoma." (PMID 33816262, 2021). "IGFBP5 primarily binds to insulin growth factors to inhibit the IGF1 and IGF2 signalling pathways, thereby inhibiting the proliferation, migration and invasion of osteosarcoma, and is a key inhibitor of in situ osteosarcoma growth and lung metastasis." (PMID 33614075, 2021). "Our results are consistent with previous work reporting a functional impact of IGF2 in maintaining relatively high autophagy levels in osteosarcoma cells (which induced an autophagic state of dormancy that protects cells against stress)." (PMID 33318299, 2020). "Expression of IGF receptor 1 (IGF1R), IGF-1, and IGF-2 have been reported in osteosarcoma cell lines and patient samples, further suggesting its role in osteosarcoma pathogenesis." (PMID 32961800, 2020). "Moreover, mRNA expression of IGF1 and IGF2 in osteosarcoma cells were increased, while the insulin receptor (INSR) and insulin receptor substrate 1 (IRS1) genes were both downregulated." (PMID 37755271, 2023). "For example, 91H promotes the progression of osteosarcoma by regulating IGF2 expression." (PMID 34048366, 2021). "Furthermore, after chemotherapy, IGF2 confers resistance correlated with enhanced autophagy when expressed at elevated levels in osteosarcomas." (PMID 33946484, 2021). "Mechanical shear force-induced IGF2 overexpression promoted MMP12 expression through PI3K signaling pathways in osteosarcoma cells, thus promoting osteosarcoma metastasis and invasion." (PMID 39744430, 2025). "Six of these genes are increased (MYOM2, VEGFA, MUC1, IHH, GLI1 and GRIA1) and seven are decreased (VCAM1, EGFR, GPC3, IGF2, GNG12, GNGT1 and C3) in localized patients with poor prognosis that either relapse or die due to osteosarcoma." (PMID 38538763, 2024). "Osteosarcoma early peak incidence occurs around early adolescence, which coincides with peak expression of circulating IGF1/IGF2." (PMID 35887382, 2022). "Since osteosarcoma cells produce high levels of IGF-2, the biological role of the autocrine loop IGF-2/IR-A may have a relevant role and should be considered in the treatment strategy of osteosarcoma." (PMID 30453495, 2018). "The effect of Imp3 on tumorigenicity of osteosarcoma cells did not appear to be mediated through Igf2-dependent mechanism." (PMID 23226335, 2012). "All mice injected subcutaneously with AXT-shIgf2 cells developed osteosarcoma tumors, and Igf2 expression in these tumors did not correlate with tumor weight." (PMID 23226335, 2012).
sarcoma (27 papers, 1991 to 2026). A usually aggressive malignant neoplasm of the soft tissue or bone. "IGF2 overexpression occurs in the majority of sarcomas, often associated with loss of imprinting at the IGF2 locus, and approximately 50% of uterine leiomyosarcomas have high IGF2 expression." (PMID 29455465, 2018). "This study identifies altered HMGA2/IGF2BP/IGF2 signaling in CIC-DUX4 sarcomas and provides proof of principle for combination therapy with trabectedin and AKT/mTOR dual inhibitors to specifically combat the disease." (PMID 34903601, 2022). "The study by Rogler and colleagues demonstrated that transgenic mice overexpressing IGF2 develop a broad spectrum of tumors, including lymphomas, hepatocellular carcinoma, sarcoma, squamous cell carcinoma, and thyroid carcinoma." (PMID 34440844, 2021). "Others have shown that DDR1 is one of the prominent molecules expressed by sarcomas characterized by constitutive IGF-2 overexpression." (PMID 28591735, 2017). "An autocrine loop involving IGF-2 and IR-A is active in different sarcomas, such as rhabdomyosarcoma and osteosarcoma cells." (PMID 24391834, 2013). "Also, the insulin receptor involves metabolic regulation and forms a hybrid receptor with IGF1R for IGF1, the latter together with IGF2, to promote the proliferation of sarcoma cells." (PMID 38338920, 2024). "However, together with IGF1R it forms a hybrid receptor for IGF1, latter together with IGF2 is thought to have a key role in driving the proliferation and survival of sarcoma cells." (PMID 25496518, 2014). "In addition, increased IGF-2 levels was described in many other sarcoma subtypes, such as rhabdomyosarcomas, leiomyosarcomas and synovial sarcomas, suggesting an autocrine/paracrine dependency on this pathway." (PMID 22415797, 2012). "Indeed we found increased expression levels for RMS-markers (Myog, Myl4, Igf2, Prox1), a FS-gene (Vcan), and LS-related genes (Pparg, Myo1e, Hoxa5, Plau), which further established the MD-tumors as mixed sarcomas consisting of RMS, FS and LS-compartments." (PMID 21533183, 2011). "The mRNA levels of IGF1 and IGF2 were enhanced, but the expression of IGF1R was unaltered in sarcoma, indicating that tumor proliferation might be promoted by an increased effect of IGF1 and IGF2." (PMID 38338920, 2024). "Although IGF2 has an important role in SS, the overexpression of IGF2 is not exclusive to this sarcoma subtype." (PMID 22550415, 2012). "There are no doubts that IGF system is important for the pathogenesis and progression of sarcomas: cells produce ligands and express the receptors creating a complex network of autocrine stimulations that may sustain tumor growth based either on IGF1/IGF1R or IGF2/IR axis." (PMID 24391834, 2013). "Even though there is not yet data available in sarcomas, this seems a plausible option for investigation in RMS where IGF2 is commonly upregulated." (PMID 21437217, 2011).